HDAC3 (histone deacetylase 3)
Diseases named in the same sentence as HDAC3 in open-access papers (continued):
Sharing a sentence is not in itself a finding about the gene and the disease.
cancer (204 papers, 2008 to 2026). A tumor composed of atypical neoplastic, often pleomorphic cells that invade other tissues. "Histone deacetylase 3 (HDAC3) is an important factor influencing anti-cancer immunity, as it regulates gene expression linked to immune cell activation and differentiation." (PMID 40006729, 2025). "Aberrant PIWIL2 expression has been implicated in promoting proliferation in HCC and other cancers, with its tumorigenic functions mediated through interactions with HDAC3, NME2, β-catenin (CTNNB1), and others via the PIWI and MID domains." (PMID 41422314, 2025). "Pharmacological inhibition of HDAC3 is cytotoxic to BRCA-deficient murine cancer organoids, an established model system for analogous human cancers." (PMID 37196082, 2023). "HDAC3 expression is not only elevated in these cancers, but is also often associated with cancer cell dedifferentiation and overall survival rate of patients." (PMID 35646715, 2022). "The elevated expression of HDAC3 has been associated with the progression of various cancer subtypes, neurodegenerative disorders, and many other human diseases." (PMID 35110603, 2022). "Dysregulation of the HDAC3-dependent gene transcription is associated with various diseases such as cancer." (PMID 34520758, 2021). "Aberrant expression and/or the localization of HDAC3 was linked with carcinogenesis in various cancers." (PMID 31430896, 2019). "Evidence of a frame shift gene mutation distinctively characterizes HDAC2 in class I. HDAC3 has documented interaction activity with cancer-associated genes (CAGE) in testicular cancers." (PMID 31683808, 2019). "In conclusion, the present work found that HDAC3 is a key regulatory factor for cancer proliferation and apoptosis, and is associated with poor prognosis in CCA patients." (PMID 28569784, 2017). "HDAC3 is involved in the regulation of cancer-associated cellular process like apoptosis, and is also important in the regulation of cancer-associated transcription factors functions, including PCAF, SRY, NF-kB and STAT proteins." (PMID 26405459, 2015). "As previously observed with HDAC inhibitor treatment, shRNA-mediated depletion of HDAC3 caused a significant (approximately 4-fold) up-regulation of the DNA damage marker γ-H2AX in cancer cells." (PMID 25026298, 2014). "Similar to cancer cells in which HDAC3 was depleted by shRNA, Hdac3-deficient MEFs also exhibited decreased expression levels of BRCA1 and ATR but increased levels of CHK1 and γ-H2AX." (PMID 25026298, 2014). "Furthermore, recent studies have indicated that HDAC3 is associated with several diseases including cancer, inflammation, and neurodegenerative disorders." (PMID 23874714, 2013). "Thus, the emergence of new, more potent and selective HDAC3 inhibitors may provide new therapeutic options for treating various cancer types while minimizing the risk of adverse effects." (PMID 38034086, 2023). "Binders, e.g., mimicking the lamin A-associated histone deacetylase HDAC3, could also be introduced to simulate changes in chromatin states in LADs, such as those occurring in senescence or cancer." (PMID 35693945, 2022). "To evaluate whether EGF-induced EGFR-c-Src activation is critical for the phosphorylation of Y328 and Y331 on HDAC3 and determine its association with the malignant behavior of cancer cells, we transiently transfected EGFR in MCF7 cells, which express low levels of EGFR." (PMID 31430896, 2019). "Furthermore, both SIRT1 and HDAC3 have been implicated as regulators of several common cellular and physiological functions such as apoptosis, circadian cycle, glucose and lipid metabolism and cancer." (PMID 23841676, 2013). "These include compounds such as RGFP966, which has demonstrated promising preclinical results in models of cancer, exhibiting selective inhibition of HDAC3 activity while sparing other HDAC isoforms." (PMID 40006729, 2025).
cancer (continued). "Second, emerging evidence reveals their critical role in shaping the tumor microenvironment (TME)—HDAC1/2 suppress antigen presentation machinery in cancer cells, while HDAC3 promotes immunosuppressive macrophage polarization." (PMID 41267925, 2025). "In this study, HDAC3 was also reported to correlate with the suppression of PD-L1 expression in cancer cells through the modification of H3 acetylation." (PMID 40941018, 2025). "The aldo-keto reductase family 1 member B1 (AKR1B1) plays a key role in cancer progression by competing with histone deacetylase 3 to bind to the deacetylase activation domain (DAD) of the nuclear receptor corepressor SMRT." (PMID 40309007, 2025). "The PCAF/HDAC3 axis links lactate metabolism to RHOA signaling, revealing lactylation as a metabolic alternative to genetic mutations in cancer progression." (PMID 41291745, 2025). "In particular, our published study has primarily investigated the multiple anti-cancer effects of HDAC3 inhibition treatment, which also shows great potential in enhancing the sensitivity of cancer immunotherapy." (PMID 40006729, 2025). "HDAC3 contributes to cancer by promoting the proliferation, survival, and metastasis of tumor cells through the regulation of gene expression." (PMID 40006729, 2025). "In essence, this study concluded that an aberrant expression of HDAC3 reversed H3 acetylation in the PD-L1 promoter region and decreased PD-L1 expression in drug-resistant cancer cells." (PMID 40941018, 2025). "Given its influence on tumor biology, HDAC3 is being studied as a potential biomarker for cancer prognosis, as well as a therapeutic target." (PMID 40006729, 2025). "Histone deacetylase 3 (HDAC3) has emerged as a critical epigenetic regulator in tumor progression and immune modulation, positioning it as a promising target for enhancing cancer immunotherapy." (PMID 40006729, 2025). "As our understanding of its mechanisms deepens, HDAC3-based therapies are poised to play a transformative role in advancing tumor immunotherapy, ultimately improving outcomes for cancer patients worldwide." (PMID 40006729, 2025). "Since HDAC3 can trigger cancer proliferation, metastasis, and angiogenesis and c-Myc is a well-known pro-tumorigenic molecule, the relationship between HDAC3, c-Myc, and B7-H6 is of particular clinical interest." (PMID 39408655, 2024). "The implications of HDAC3 inhibition extend beyond cancer therapy, encompassing a wide range of complex diseases." (PMID 39005934, 2024). "This agrees with the ability of HDAC3 to restrain apoptosis induced by several stimuli in different cancer cell types." (PMID 39107280, 2024). "Malic enzymes (ME), as sources of NADPH, accelerate the combination of NADPH and histone deacetylases 3 (HDAC3) in cancer cells and adipocytes, and influence the level of epigenetics." (PMID 37345046, 2023). "For example, HDAC3 was upregulated in most cancer types, including LUAD (log2FC = 0.18, adj.P = 2.94E-09) and LIHC (log2FC = 0.26, adj.P = 1.36E-07), but was down-regulated in KICH (log2FC = -0.21, adj.P = 2.53E-04) and THCA (log2FC = -0.07, adj.P = 1.15E-04)." (PMID 37553641, 2023). "HDACs and DNMT3B act as transcriptional repressors for tumor suppressor genes, high mRNA levels of HDAC3 and DNMT3B are associated with poor prognosis in patients with different types of cancer." (PMID 36870998, 2023). "We also found that the HDAC3 knockdown in cancer cells inhibits EMT markers and activates ER stress in vivo." (PMID 34973135, 2023). "HDAC3 is necessary to prevent DNA replication stress, thus its inhibition can accumulate lethal DNA damage in cancer cells." (PMID 37509312, 2023).
cancer (continued). "In fact, the relationship between HDAC3 and epithelial mesenchymal transition has been reported in malignant tumors and other diseases." (PMID 37553641, 2023). "This provides new insights into the mechanism by which HDAC inhibitors are used to target HDAC3 in cancer treatment." (PMID 35189899, 2022). "As a member of the HDACs family, histone deacetylase 3 (HDAC3) has been often activated in several cancers and therefore, its selective inhibitors constitute a preventive strategy against these cancers." (PMID 35578338, 2022). "A plethora of literature describes the pathophysiological role of HDAC3 in a variety of human cancers, neurodegenerative disorders, diabetes, inflammatory and cardiovascular diseases." (PMID 35110603, 2022). "Among Class I HDACs, the HDAC3 is aberrantly expressed in many malignancies and plays a significant role in the progression of cancer and many other human diseases." (PMID 35110603, 2022). "HDAC3 has been highlighted to be a crucial validated target for cancer due to its overexpression in a variety of cancers." (PMID 35578338, 2022). "From the mechanical point of view, glutamine deprivation activated mTORC2 to promote HDAC3‐mediated deacetylation and stabilization of GS, which involved in the supporting stemness of cancer cells." (PMID 35187863, 2022). "Western blotting data further exhibited higher expression of HDAC3 in cancer tissues than in normal bile duct tissues." (PMID 35126526, 2022). "Collectively, an HDAC3 selective inhibitor (D28) with potent in vitro anticancer activity was developed as a lead compound for the treatment of cancer." (PMID 35910736, 2022). "HDAC3 plays an important role in the progression of malignant tumors, especially in proliferation, apoptosis, metastasis, angiogenesis and anticancer drug resistance." (PMID 34991620, 2022). "Collectively, the current results exhibited the potential of HDAC3 selective inhibition in the treatment of cancer." (PMID 35910736, 2022). "Class I histone deacetylases, HDAC1, HDAC2, and HDAC3, represent potential targets for cancer treatment." (PMID 35458724, 2022). "The class I HDACi entinostat (MS-275) is a synthetic benzamide derivative with preference for HDAC1 and HDAC3 enzymes undergoing clinical trials for several types of cancer." (PMID 35994477, 2022). "In the landscape of epigenetic regulation, histone deacetylase 3 (HDAC3) has emerged as a prominent therapeutic target for the design and development of candidate drugs against various types of cancers and other human disorders." (PMID 35110603, 2022). "It is noteworthy that the implication of PDCD5/HDAC3/miR-195-5p/SGK1 axis in RCC has been rarely studied through their respective interaction which has been briefly mentioned in other cancers." (PMID 36266728, 2022). "Among the HDACs, HDAC3 was identified to suppress PD-L1 expression in cancer cells through histone acetylation modifications." (PMID 32024543, 2020). "Previouse reported showed that HDAC3 plays crucial roles in cancer stem cells via genome wide epigenetic modifications." (PMID 32404892, 2020). "In conclusion, enhanced histone H3 acetylation of the PD-L1 promoter via the COP1/c-Jun/HDAC3 axis was crucial for the PD-L1 increase in drug-resistant cancer cells." (PMID 32024543, 2020).
cancer (continued). "Ubiquitination of HDAC3 resulted in a decreased level of histone acetylation and finally led to upregulation of cancer stem cell-related genes." (PMID 32404892, 2020). "It was shown that only the pan-HDAC inhibitor SAHA and the HDAC3-specific inhibitor RGFP966 markedly increased PD-L1 expression in all the parental cancer cells in our study, suggesting the important role of HDAC3." (PMID 32024543, 2020). "Malme3MR cells show low expression level of HDAC3 compared to parental anti-cancer drug sensitive melanoma cells (Malme3M)." (PMID 32626712, 2020). "Enhanced histone H3 acetylation of the PD-L1 promoter via the COP1/c-Jun/HDAC3 axis was crucial for the PD-L1 increase in drug-resistant cancer cells." (PMID 32024543, 2020). "It was demonstrated that c-Jun knockdown by siRNAs increased HDAC3 expression in drug-resistant cancer cells in our study." (PMID 32024543, 2020). "Most importantly, the ubiquitination level of HDAC3 was responsible for USP38 mediated regulation of cancer stem cell-related transcripts." (PMID 32404892, 2020). "USP38 functions as a tumor suppressor through modulating the ubiquitination of HDAC3, which further controls the expression of cancer stem cell-related genes." (PMID 32404892, 2020). "HDAC4 interacts with HDAC3 via N-CoR, has been found overexpressed in breast cancers, and is used as a cancer progression marker in esophageal carcinomas." (PMID 31683808, 2019). "The elevation of HDAC3 activity is presumably necessary for the cancer cells to maintain their malignant phenotype." (PMID 30866966, 2019). "Due to the overexpression of HDAC3 in a variety of cancers, it is an important potential target for cancer." (PMID 31049076, 2019). "HDAC3 is considered a major target for therapeutic benefits of many HDIs in cancer, immune diseases, metabolic disorders, and neurological diseases." (PMID 30428023, 2019). "HDAC3 inhibition is considered to be of therapeutic benefit against cancer, immune diseases, metabolic disorders, and neurological diseases." (PMID 30428023, 2019). "We found cMyc decreases pyruvate levels by promoting LDHA and PKM2 levels, this can consequently decrease the inhibition to HDAC3 and protect cancer cells from apoptosis." (PMID 30866966, 2019). "Effects of HDAC3 on anaphylaxis, cellular interactions involving mast cells and macrophages during anaphylaxis, and any tumorigenic potential of cancer cells enhanced by mast cells will be discussed in this review." (PMID 31597362, 2019). "The protein Deleted in Breast Cancer-1 is a regulator of several transcription factors and epigenetic regulators, including HDAC3, Rev-erb-alpha, PARP1 and SIRT1." (PMID 31591441, 2019). "HDAC3, a member of HDACs family, overexpressed in various cancer cells, has been shown to regulate proliferation and apoptosis of cancer cells." (PMID 29555935, 2018). "Decreased expression of HDAC3 decreases expression levels of miR-200b, miR-217, and miR-335 to confer anti-cancer drug resistance." (PMID 30583572, 2018). "In this paper, we report the roles of microRNAs that regulate the expression of HDAC3 and CAGE involved in resistance to anti-cancer drugs and associated mechanisms." (PMID 30583572, 2018). "HDAC3 inhibits the angiogenic potential of cancer cells by decreasing expression levels of angiogenic factors, such as VEGF and plasminogen activator inhibitor-1 (PAI-1)." (PMID 30583572, 2018). "Knockdown of HDAC3 reduced the effect of PIWIL2 on cancer cell proliferation or apoptosis, indicating that HDAC3 was involved in the role of PIWIL2 on cancer proliferation and apoptosis." (PMID 29555935, 2018). "In this review, roles of HDAC3-miRNAs-CAGE molecular networks in resistance to anti-cancer drugs, and the relevance of HDAC3 as a target for developing anti-cancer drugs are discussed." (PMID 30583572, 2018).
cancer (continued). "Western blot results showed that HDAC1, HDAC2, and HDAC3 expression change between cancer, and adjacent tissue was consistent with the B7-H1 level change in 8 (66.7%), 9 (75.0%), and 9 (75.0%) cases, respectively." (PMID 30537988, 2018). "The reduced stabilization and phosphorylation of HDAC3 caused by PIWIL2 knockdown inhibits cancer cell proliferation and increases cancer cell apoptosis." (PMID 29555935, 2018). "Our present study firstly revealed that PIWIL2 can play a role in HDAC3-mediated epigenetic regulation on cancer cell proliferation and apoptosis." (PMID 29555935, 2018). "MI192 inhibited cancer cell proliferation through the induction of cell apoptosis primarily through targeting HDAC3." (PMID 28569784, 2017). "MI192 is a novel HDAC3-specific inhibitor that displays antitumor activity in many cancer cell lines." (PMID 28569784, 2017). "A meta-analysis of a variety of human cancers revealed that HDAC3 is one of the most frequently up-regulated genes in cancer cells." (PMID 29088860, 2017). "It is our belief that HDAC3 is an important regulatory factor of proliferation, growth homeostasis, and apoptosis of cancer cells during various cellular events." (PMID 27462923, 2016). "Nevertheless, further studies are necessary to confirm the specific involvement of HDAC3 in the regulation of TP expression in cancer cells." (PMID 26735339, 2016). "The interaction between the cancer cells and macrophages is mediated by IL-6 produced under the regulation of HDAC3 translocation to the nucleus in the cancer cells." (PMID 26745602, 2016). "This study demonstrates a novel pathway of interaction between cancer cells and tumor promoting macrophages involving HDAC3 and IL-6." (PMID 26745602, 2016). "A recent study using 115 ovarian tumour tissues confirmed that expression of nuclear HDAC1, HDAC2 and HDAC3 proteins increased stepwise in benign, borderline and malignant tumours." (PMID 26560874, 2016). "HDAC3 (histone deacetylases 3), a member of class I HDACs, is overexpressed in the majority of carcinomas, and is one of the most frequently upregulated genes in cancer." (PMID 26918727, 2016). "An analysis of a wide range of human cancers showed that HDAC3 was expressed at high levels in many cancerous tissues and cell lines, including PC3 cells." (PMID 26450925, 2015). "To date, SIRT1 and HDAC3 appear to be complex regulatory factors with multiple roles in cell biology and transcriptional regulation and have been suggested as anti-cancers targets." (PMID 26405459, 2015). "Selectively inhibiting HDAC3 has been suggested to hold promise in treating a range of diseases, from inflammation, to neuro-protective effects and cancer therapy." (PMID 26450925, 2015). "Histone deacetylase 3 (HDAC3) is overexpressed in cancers and its inhibition enhances anti-tumor chemotherapy." (PMID 25623232, 2015). "Class I histone deacetylases, like HDAC3, are repressing the transcription machinery for various genes in cancer." (PMID 25264628, 2014). "The shRNA-mediated depletion of HDAC3 also reduced the levels of p-ATR and p-CHK1 in HeLa cells, indicating that HDAC3 depletion inhibits the ATR-CHK1 pathway in cancer cells." (PMID 25026298, 2014). "Our group and others have shown that inhibiting class I HDACs, particularly HDAC3, inhibits cellular growth and survival, and de-represses p21 transcription leading to increased protein expression in cancer cell lines of diverse origin." (PMID 24904826, 2014). "We previously found that the transcription factors MEF2D and GATA3, as well as the histone deacetylases HDAC3 and HDAC9, regulate BRM expression in BRM-deficient cancer cell lines." (PMID 24913006, 2014).